CYP4Z2P (cytochrome P450 family 4 subfamily Z member 2, pseudogene)
Synonyms: FLJ40054
Gene: Transcribed unprocessed pseudogene on chromosome 1 (46,843,178 to 46,900,434, reverse strand). Ensembl gene ENSG00000154198.
Subcellular location: Membrane
Diseases named in the same sentence as CYP4Z2P in open-access papers:
CYP4Z2P is named in the same sentence as 7 diseases in open-access papers, as found by Europe PMC text mining. Sharing a sentence is not in itself a finding about the gene and the disease. The quoted sentences say what the papers report.
breast carcinoma (8 papers, 2010 to 2026). "We observed over-expression of LIMCH1, a gene encoding zinc-binding protein, and also four genes encoding iron-binding proteins (LTF, SLC40A1, CYP4Z1 and CYP4Z2P) previously linked to breast cancer." (PMID 21209903, 2010). "For instance, CYP4Z2P maintains the stemness of breast cancer cells, and pseudogene CYP2A7 affects CYP2A6 expression in human liver." (PMID 33931030, 2021). "Furthermore, it is demonstrated that six2 can increase the expression of CYP4Z1 and CYP4Z2P and also activate ceRNET_CC by binding to their promoters, which in turn promotes the stemness of breast cancer cells." (PMID 41431719, 2026). "Notably, the expression of CYP4Z1 and CYP4Z2P displayed a positive correlation in clinical breast cancer samples (P < 0.001)." (PMID 30832689, 2019). "Moreover, overexpression of CYP4Z1 and/or CYP4Z2P in breast cancer cells may promote transcriptional activity of oestrogen receptors, stemness, and tamoxifen resistance." (PMID 34590601, 2021). "Pseudogenes were reported to correlate with varies of diseases, such as CYP4Z2P related to breast cancer, while it has not been investigated in glioma." (PMID 25880120, 2015). "Additionally, we detected whether the six2-mediated promotion of breast cancer cell stemness occurs through the downstream effectors of the ceRNA network between CYP4Z1 and the pseudogene CYP4Z2P and the hTERT/PI3K/Akt and ERK1/2 pathways." (PMID 30832689, 2019).
hypospadias (1 paper, 2020). Hypospadias is the displacement of the urethral meatus on the ventrum of the penis. "We identified a significant causal effect of methylation at cg04714159 on hypospadias, as well as potential causal effects of multiple members of the cytochrome P450 family of enzymes in this region (CYP4A11, CYP4A22, CYP4B1, CYP4X1, CYP4Z2P)." (PMID 32728162, 2020).
inflammatory skin disease (1 paper, 2023). Inflammatory skin disorders covers a broad category that includes many conditions ranging in severity, from mild itching to grave medical health complications These disorders are common in people of all ages and races. "Additionally, EPHA1-AS1, CYP4Z2P and SNHG12 gene upregulation have all been previously linked to inflammatory skin diseases." (PMID 38003532, 2023).
psoriasis (1 paper, 2023). An autoimmune condition characterized by red, well-delineated plaques with silvery scales that are usually on the extensor surfaces and scalp. "We also corroborated the involvement of eight lncRNA genes involved in psoriasis as determined by previous studies, including EPHA1-AS1, CYP4Z2P, SNHG12, LINC01215, LINC1206, SH3PXD2A-AS1 and CERNA2." (PMID 38003532, 2023).
cancer (3 papers, 2019 to 2023). A tumor composed of atypical neoplastic, often pleomorphic cells that invade other tissues. "Angiogenesis is a fundamental process in the growth and progression of tumors, and miR-197 promotes angiogenesis in cancer by increasing the VEGF-A/VEGFR2 pathway by binding to the CYP4Z2P and CYP4Z1 genes, and by activating the PI3K/pathways AKT and ERK1/2." (PMID 36143221, 2022).
CYP4Z2P also shares sentences with these, for which no sentence is quoted: glioma (1 paper); tumor (1).